EPHA2 (EPH receptor A2)
Diseases named in the same sentence as EPHA2 in open-access papers (continued):
Sharing a sentence is not in itself a finding about the gene and the disease.
infection (continued). "There is evidence that EphA4 may also be an entry receptor for KSHV; EphA4 expression has been detected in KSHV target cells and an EphA2-EphA4 double-knockout resulted in a greater reduction in infection than EphA2 or EphA4 single knockouts." (PMID 33430066, 2021). "It is possible that the dependence on EPHA2 may be reduced when virus is directly transferred in this manner, implying transfer infection may require additional receptors, such as integrins." (PMID 33596248, 2021). "Additionally, incomplete reduction of infection upon EPHA2 knock out in endothelial cells and fibroblasts suggests that additional receptors are used by KSHV for entry, likely other EPH receptors." (PMID 33477296, 2021). "Additionally, EPHA7 was found to be expressed at high levels in a PEL cell lines, along with EPHA2, suggesting a role for these two receptors in the infection of cells that eventually develop into PEL." (PMID 33477296, 2021). "Recently, it was reported that another β-glucan-recognizing receptor, EphA2, is also involved in the internalization of A. fumigatus conidia during infection and might be modulated by DHN-melanin." (PMID 34338598, 2021). "We found that when EGFR was either knocked down with siRNA or inhibited with the specific EGFR kinase inhibitor, gefitinib, C. albicans-induced phosphorylation of EphA2 was transient, occurring within 30 min of infection, but declining to basal levels by 90 min." (PMID 33471869, 2021). "It is also possible that there is a temporal regulation and that different EphA2 signaling pathways are activated during the primary infection (canonical, which would stimulate virus internalization via endocytosis) and reactivation (noncanonical, which would increase cellular oncogenic potential)." (PMID 34499637, 2021). "A comparison of the transcriptional profile of the EphA receptor subfamily in whole brain tissue isolated from mice infected with PbA revealed a significant upregulation of EphA2 transcript at day 6 post-infection at the onset of ECM symptoms along with a slight upregulation of EphA1 transcript." (PMID 31999807, 2020). "Along with the data presented in this study, it suggests that an approach aimed at blocking/inactivating EphA2 could have significant implications for targeting both liver-stage and blood-stage infections." (PMID 31999807, 2020). "In accordance with our hypothesis, exposure of EPHA2 knockout cell lines to S. aureus resulted in reduced intracellular bacterial load even at early time points of infection." (PMID 30890742, 2019). "Since the proportion of traversed cells usually exceeds that of productively invaded cells, we reasoned that the correlation observed between EphA2 levels and infection rates could be due to an effect on cell traversal rather than infection." (PMID 29975762, 2018). "The crucial role of EphA2 for chlamydial replication and its long-lasting upregulation in the course of infection may have another important consequence." (PMID 25906164, 2015). "We could demonstrate that EphA2 is required to maintain apoptosis resistance during C. trachomatis serovars L2 and D infection." (PMID 25906164, 2015). "As we found increased Akt activation in EphA2 overexpressing-infected cells and interaction of activated PI3K with EphA2 during early infection, we next determined whether increased total EphA2 during late Ctr infection also associates with activated PI3K." (PMID 25906164, 2015). "Interestingly, at 3 h p.i., the total amount of EphA2 already started to increase and the elevated surface display was reduced to the level of uninfected cells and remained stable until the end of the infection cycle." (PMID 25906164, 2015). "Thus, at least two different serovars of C. trachomatis appear to be capable of interacting with EphA2 to amplify signals crucial for infection." (PMID 25906164, 2015). "Indeed, EphA2 overexpression resulted in increased pAkt levels in uninfected cells, which further increased upon Ctr infection." (PMID 25906164, 2015).
infection (continued). "CIB1 knockdown significantly reduced the infection induced EphA2, Src and Erk1/2 activation." (PMID 24550731, 2014). "For the time-dependent regulation of EPHA2 we could show that the regulated tyrosine during early infection is the phosphorylated Y588/Y594 position, while Y575 is only regulated later during infection." (PMID 25101063, 2014). "To determine the mechanism by which CIB1 plays a role in KSHV entry and infection, we next determined whether CIB1 associates simultaneously with components of the EphA2 assembled multi-molecular signal complex such as Src, PI3-K, and c-Cbl." (PMID 24550731, 2014). "In HFF cells, KSHV infection induces the association of EphA2 with c-Cbl very early during infection which directs the K63 specific rather than K48 type of polyubiquitination of EphA2." (PMID 23874206, 2013). "Therefore, we determined the kidney fungal burden in WT and Epha2–/– mice 4 days post infection." (PMID 36138043, 2022). "KSHV‐associated pathogenesis subsequent to infection is likely influenced by an orchestrated concert of innate immune system interactions (NK‐KIR‐HLA), downstream inflammatory pathways (interleukins, NK cell activation) and oncogenic mechanisms (EPHA2 oncogenic pathways)." (PMID 33043529, 2021). "Interestingly, brain EphA2 upregulation is a unique feature of infection with the ECM-causing PbA strain and does not occur upon infection with strains that do not cause ECM." (PMID 31999807, 2020). "The infection process of EBV relies on interactions between the virus and specific receptors on the surface of host cells, including CD21, NRP1, EphA2, and, more recently, discovered receptors such as R9AP and DSC2." (PMID 42112902, 2026). "Three days post-infection, the qPCR analysis showed that HCMV copy number was reduced in GBOs pretreated with EphA2 inhibitors in a dose-dependent manner." (PMID 37146061, 2023). "Treatment of mice with gefitinib inhibited C. albicans-induced phosphorylation of both EphA2 and EGFR in the oral epithelial cells, and reduced the tissue levels of CXCL1/KC, CCL20, and S100A8 after both 1 and 2 days of infection." (PMID 33471869, 2021). "Using EPHA2 downregulation at 24 h post-infection as a readout of early receptor activation, we found that pre-incubation with PP2, an SRC family kinase (SFK) inhibitor, prevented H. pylori-induced EPHA2 downregulation when compared with vehicle-treated cells." (PMID 32102381, 2020). "We found that both EphA2 and EphA4 play a role in KSHV fusion and infection, since EphA2-EphA4 double-knockout cells had the greatest decrease in fusion activity and infection compared to single-knockout cells." (PMID 30782663, 2019). "The global network notably recognizes six proteins (EPHA2, FBL, PFKM, PSMA5, SSR1, and TFRC) for their involvement in the infection of cells (p: 9.58 × 10− 4)." (PMID 31159726, 2019). "Studies show that Ephrin receptor A2 (EphA2) binds to gHgL and internalizes KSHV, resulting in the infection of endothelial cells." (PMID 31752107, 2019). "Thus, the EPHA2 basal levels may be indirectly controlled by Hla during S. aureus cell infection." (PMID 30890742, 2019). "In order to confirm these findings in another cell type, we analyzed the effects of EphA2 silencing in HepG2/CD81 cells, using flow cytometry to quantify PyGFP-infected cells 24 hours post-infection." (PMID 29975762, 2018). "Accordingly, compared with the control groups, at 48 h post-infection (p.i.), we observed a dramatic inhibition of nuclear LANA immunostaining in AR and EphA2 siRNA-treated SLK cells." (PMID 28957431, 2017). "We examined the effect of wild-type or early-region gene-mutated adenovirus [E1B-55k-(dl1520), E4orf3-(pm4150), E4orf6-(pm4154), E4orf3-/E4orf6-(pm4155)] infection on ALCAM, EPHA2 and PTPRF." (PMID 28631589, 2017). "Both chemical inhibition of EphA2 kinase activity and of PI3K prevented Ctr infection if the inhibitor was added either prior to or simultaneously with infection." (PMID 25906164, 2015).
infection (continued). "The interaction was further verified by confocal microscopy showing the co-localization of EphA2 with activated PI3K after Ctr infection, suggesting that PI3K activation is an important function of intracellular EphA2 in Ctr infection." (PMID 25906164, 2015). "Since our results demonstrated that infection also induced the enhanced association of CIB1 with LRs of infected cells and CIB1 plays a role in macropinocytosis, we rationalized that CIB1 might interact with LR associated KSHV entry receptors especially EphA2 early during infection." (PMID 24550731, 2014). "Taken together, these studies demonstrated that EphA2 clearly has a positive role in clathrin mediated entry of KSHV and its trafficking towards early endosomes presumably for productive infection." (PMID 23874206, 2013). "To prove that EphA2 polyubiquitination is a result of KSHV infection, we used heparin-treated KSHV for infection." (PMID 23874206, 2013). "Furthermore, during infection, EGFR and the ephrin type-A receptor 2 (EphA2) form a complex and activate each other mutually." (PMID 40293285, 2025). "Unlike a previous study that reported a modest enhancement of MHV68 fusion by murine EphA2, neither human nor murine EphA2 bound to MHV68 gH/gL or influenced MHV68 infection in our assays." (PMID 41118409, 2025). "One study proposed that P36 interacts with the ephrin receptor EphA2 on hepatocytes to mediate infection, but direct evidence for such an interaction is lacking, and EphA2 was later shown to be dispensable for sporozoite productive invasion." (PMID 36761022, 2023). "If other viral protein(s) are found to mediate entry, the cognate receptor, likely EphA2, NRP1, or integrins, can be identified, though it is possible that an as yet unidentified EBV receptor may also contribute to infection." (PMID 36630458, 2023). "Based on their localization, it is likely that integrins function as the EBV receptor for infection at the basal layer, whereas it is likely EphA2 and NRP1 function as EBV receptors for infection at the apical surface and within the suprabasal layers where productive replication occurs." (PMID 36630458, 2023). "Furthermore, IL-23 p19 depletion in Epha2–/– mice increased kidney injury, while TREM1 levels were similar after 3 days of infection." (PMID 36138043, 2022). "To evaluate, whether EPHA2 could also allow infection of EBV into primary cells, we examined expression of EPHA2 in organoids." (PMID 33596248, 2021). "Knockout of EPHA2, however, resulted in a significantly reduced but not completely abolished level of infection." (PMID 33477296, 2021). "Together, the reduced cytokine and chemokine production from brain endothelial cells in the absence of EphA2 explain the lack of CD8+ T cells found in the brains of EphA2-/- mice during PbA infection and the resulting improvement in survival." (PMID 31999807, 2020). "For long periods of time post-infection, H. pylori induces EPHA2 protein downregulation without affecting its mRNA levels, an effect preceded by receptor activation via phosphorylation." (PMID 32102381, 2020). "This brain-specific EphA2 upregulation likely results from the fact that LT-α is only upregulated in the brain during ECM with little to no increase in LT-α mRNA levels in the liver, lung, or spleen at day 6 post-infection with PbA." (PMID 31999807, 2020). "EPHA2 was tyrosine-phosphorylated as early as 30 min and maintained for up to 3 h post-infection, at which point no alterations in the total protein levels of EPHA2 were observed." (PMID 32102381, 2020). "At 24 h post-infection, neither tyrosine-phosphorylated nor total EPHA2 were detected, suggesting receptor degradation upon activation." (PMID 32102381, 2020). "As EphA2 protein sequences are highly conserved across species, and as both AIHV-1 and EHV-2 gHgL proteins bind to human EphA2, these γ-herpesviruses have the cross-species infection potential." (PMID 33235207, 2020).
infection (continued). "In mice, EphA2 is upregulated by LT-α, a cytokine required for BBB breakdown in PbA infection." (PMID 31999807, 2020). "Since fusion levels are not altered in the EphA2 and EphA4 kinase-dead mutants, it is likely that the kinase function is important for infection by functioning in endocytosis following virus binding." (PMID 30782663, 2019). "The integrin receptors and xCT are likely nonessential for infection and only required for the initial binding of the virus to cells, whereas EphA2 is essential because it triggers fusion upon virus binding to epithelial cells." (PMID 30782663, 2019). "We, in addition, concluded that the rapid increase and decline in cell surface exposed EphA2 during early infection time-points is independent of changes in total EphA2." (PMID 25906164, 2015). "Akt activation is dependent on EphA2 during mid-phase (16 to 24 h) but not late-phase Ctr infection (48 h), in line with its role in anti-apoptosis signaling during the replicative phase." (PMID 25906164, 2015). "At 90 min post-infection, the EPHA2 Y575 phosphosite was not regulated but the Y588/Y594 phosphosite was." (PMID 25101063, 2014). "Consistent with our previous finding, EphA2 was observed strictly in uninfected HMVEC-d cell LR (LR lanes 1–4) but not in NLR fractions (NLR, lanes 1–4), which also remained unchanged with infection." (PMID 24550731, 2014). "Since the non-LR region constitutes most of the cellular area enriched with all of the KSHV entry receptors, distribution of EphA2 at the non-LR region of HFF cells probably provides a good platform for the initiation of infection." (PMID 23874206, 2013). "Compared to mock infection, early during KSHV infection (5 and 10 min p.i.), a significant colocalization was observed between p-EphA2 and p-c-Cbl or clathrin predominantly at the periphery of infected HFF cells (white arrows) with concomitant reduction of association at 30 min p.i.." (PMID 23874206, 2013). "Interestingly, infection with a non-uropathogenic E. coli K-12 also elevated total EPHA2 levels comparable to that of uropathogens." (PMID 36297233, 2022). "To gain insight into which signaling pathways were involved in EPHA2 activation induced by H. pylori leading to receptor downregulation at late time-points (24 h), we incubated MKN74 cells with chemical inhibitors of common signaling pathways involved in EPH and EFN signaling prior to infection." (PMID 32102381, 2020). "However, in our hands, there was no clear correlation between the infection rate and EphA2 expression level." (PMID 29975762, 2018). "Also, co-silencing EphA2 together with PDGFRβ had no additive effect, suggesting that Ctr does not employ the PDGFRβ during mid-phase infection." (PMID 25906164, 2015). "Interestingly, in contrast to ligand-induced EphA2 degradation, EphA2 was not degraded in the cell during Ctr infection." (PMID 25906164, 2015). "It was further revealed that the overexpression of EphA2 promotes EBV infection in epithelial cells, while knocking out EphA2, or pretreatment with the soluble EphA2 protein, EphA2-blocking antibody, or EphA1 (natural ligand of EphA2), could significantly reduce epithelial cell infection." (PMID 36366470, 2022). "Using small interfering RNA (siRNA) and antibodies against EphA2, combined with direct detection of parasites by flow cytometry or microscopy, we show that blocking EphA2 has no significant impact on P. yoelii or P. berghei host cell infection, irrespective of the entry route." (PMID 29975762, 2018). "Overall, our studies reveal EphA2 as a critical non-LR region associated molecule in fibroblast cells which coordinates the signals induced during interaction of KSHV with its entry receptors and regulates the endocytic events leading to clathrin mediated entry and productive infection." (PMID 23874206, 2013).
infection (continued). "Ephrin receptor A2 (EPHA2) was identified as a receptor for EBV entry into epithelial cancer cell lines, yet the physiological relevance of its role in infection of healthy gastric epithelium was not explored." (PMID 33596248, 2021). "Previous studies suggested that the localization of EPHA2 protein varies between epithelial cell lines and primary cells, pointing to the possibility that although expressed at similar levels, the protein may not be accessible for infection in primary cells compared to transformed cells." (PMID 33596248, 2021). "Contrarily, we observed no influence of saturating concentrations of EphA2-Fc/EphB3-Fc on the infection with Eph-binding-negative mutants KSHV gH-ELAAN, RRV gH-AELAAN or RRV ΔgL when compared to infection with untreated or soluble Fc treated viral inocula." (PMID 29432452, 2018). "In contrast to EphA2, PDGFRβ is downregulated during Ctr infection and no significant changes were observed for PDI or EphB4 expression, suggesting that EphA2 is specifically upregulated and activated during Ctr infection." (PMID 25906164, 2015). "Overexpression of full length EphA2, but not the mutant form lacking the intracellular cytoplasmic domain, enhanced PI3K activation and Ctr infection." (PMID 25906164, 2015).
adenocarcinoma (4 papers, 2014 to 2021). A common cancer characterized by the presence of malignant glandular cells. "Moreover, elevated EphA2/ephrin-A1 expression was associated with female gender, reduced smoking status, adenocarcinoma type, well differentiated and p-stage IA NSCLC and EGFR gene mutations." (PMID 24495444, 2014). "Endogenous Pparγ1 enhanced EphA2 mRNA and protein abundance in the ErbB2 adenocarcinoma." (PMID 33946495, 2021).
cardiovascular disease (3 papers, 2018 to 2020). "Reduced progression to advanced atherosclerotic plaques in EphA2(−/−)ApoE(−/−) mice suggests that EphA2 has an essential function in the early stage of cardiovascular disease." (PMID 33510642, 2020). "The present study illustrated that PGRN plays a previously unrecognized role in Hcy-induced endothelial injury, which is achieved through its interaction with EphA2 signaling, implying a promising therapeutic target for cardiovascular disease." (PMID 33510642, 2020). "In summary, our findings illustrate that PGRN exerts a previously unrecognized role in Hcy-induced endothelial injury, which is achieved through the interaction of EphA2 signaling, implying that it is a prognostic marker or a promising therapeutic target for cardiovascular disease." (PMID 33510642, 2020).
digestive system tumors (2 papers, 2021 to 2025). "We previously reported that EphA2 is frequently overexpressed and correlated with increased cell proliferation, invasion and migration ability of gastrointestinal tumours." (PMID 33586348, 2021).
bacterial infections (1 paper, 2022). "Our data showed increased EPHA2 expression as well as activation upon bacterial infection." (PMID 36297233, 2022).
kidney disease (1 paper, 2022). "Further studies are needed to find out if EphA2 levels are associated with renal measures in patients with other types of kidney disease and whether they can predict future renal function decline." (PMID 36553030, 2022). "Revealing the roles of EphA2 and the other types of Eph receptors in kidney disease will be important in the future." (PMID 36553030, 2022).
neurological diseases (1 paper, 2024). "For example, SLP1, sortilin, and EPHA2 are specifically distributed in the nervous system and function in neurological diseases; CCNT1 is related to HIV infections; while TNFRs (TNFR1, TNFR2) are associated with inflammatory regulation, of which TNFR2 usually involves anti-inflammatory responses." (PMID 38689292, 2024).